LEP (leptin)
Diseases named in the same sentence as LEP in open-access papers (continued):
Sharing a sentence is not in itself a finding about the gene and the disease.
Obesity (continued). "Leptin levels increase in states of energy excess, such as in obesity and overconsumption of calories, but the effect of leptin in the central nervous system is blunted due to leptin resistance." (PMID 27891164, 2016). "We previously determined that obesity in BBS mutant mice (Bbs1M390R, Bbs2-/-, Bbs4-/- and Bbs6-/-) was associated with hyperphagia and leptin resistance." (PMID 26926121, 2016). "Diet-induced obesity in both humans and animals results in increased adiposity, as well as the gradual failure of the anorexigenic hormone leptin to regulate intake and metabolic homeostasis, a phenomenon known as leptin resistance." (PMID 27257625, 2016). "Among women with excessive weight gain in gestational week 29, women in obesity class III had significantly higher leptin levels compared to those in obesity class II." (PMID 27257506, 2016). "At 29 weeks gestation measurement women with excessive weight gain had a significantly higher leptin levels than women in obesity class II." (PMID 27257506, 2016). "Failure of central leptin action in rodent models of obesity therefore leads to infertility due to hypogonadotrophic hypogonadism and follicle development." (PMID 27375552, 2016). "It was shown that five gavage doses of SB significantly alleviated HF diet-induced obesity and restored plasma glucose, insulin and leptin to control levels." (PMID 27528227, 2016). "The increased leptin levels found in the HAGE-HF fed mice suggest the leptin resistance to obesity and fatty liver, as well as the inflammation in these fatty livers." (PMID 26942201, 2016). "In summary, we demonstrated the development of atrophic gastritis using a murine model of diet-induced obesity with an enhanced leptin-ObRb signaling pathway." (PMID 26839577, 2016). "Middle-aged adults born with a low weight present a higher prevalence of diabetes and obesity and also higher leptin levels and leptin to fat mass ratio than adults born with a normal weight." (PMID 27141948, 2016). "Leptin is important for regulating body fat, but in obesity, leptin concentrations are elevated and individuals can become “leptin resistant” resulting in increased weight gain [reviewed in detail]." (PMID 27023786, 2016). "This study was designed to explore the relationships of leptin and adiponectin with various anthropometric indexes of obesity, blood lipids and insulin resistance among a Cameroonian population." (PMID 27189377, 2016). "Concentrations of maternal serum IGF-I and leptin are decreased in intrauterine growth restriction (IUGR) while pregnancies associated with obesity and diabetes have higher maternal serum IGF-I, insulin, and leptin." (PMID 26858656, 2016). "In mouse models of diabetes and obesity, liver feminization was consistently observed and was at least partially reversed by leptin or resveratrol exposure." (PMID 26959237, 2016). "Leptin is secreted by adipocytes and is present in increased concentrations in obesity, consistent with what we report in our female mice with high-fat diet induced obesity." (PMID 27695036, 2016). "The suppression of Rap1 protect against obesity and metabolic disorders through the regulation of food intake and maintaining leptin and insulin signaling." (PMID 27812350, 2016). "Leptin resistance is emerging as an important factor in obesity, so a greater understanding of the relationship between stress and leptin will help to elucidate leptin’s connection to obesity." (PMID 26872268, 2016). "Our results implicated the potential application of ASI and its derivatives in the prevention of obesity as anti-leptin resistance agents." (PMID 27444146, 2016). "Leptin is a 16 kDa protein that is the product of the ob gene and found in excessive levels in obesity." (PMID 27746739, 2016). "LEP has been proposed as a culprit for obesity-induced cancer because it displays epigenetic variation and is involved in energy homeostasis, immune responses, angiogenesis and insulin signaling." (PMID 27703473, 2016).
Obesity (continued). "Leptin plays a key role in the pathogenesis of obesity and depression via the long form of leptin receptor (LepRb)." (PMID 27739518, 2016). "Maternal and fetal glucose, lipid profile, adiponectin, leptin, and resistin levels were analyzed by obesity and maternal weight gain." (PMID 27190514, 2016). "In a murine model for obesity and diabetes, leptin resistance was shown to promote AD-relevant tau pathology." (PMID 27429752, 2016). "In fact, obesity is associated with a hyperexpression of TNF-α and other adipokines (e.g., IL-6, leptin, adiponectin) and transforming growth factor-β, which leads to a chronic proinflammatory state." (PMID 27964760, 2016). "Obese patients often have leptin resistance and high serum levels of leptin, which exacerbate obesity and hypertension owing to a sustained increase in sympathetic nerve activity." (PMID 27296438, 2016). "Leptin and insulin actively participate in energy metabolism and their elevations in blood correlate with metabolic disturbance in rodent models of obesity." (PMID 27582541, 2016). "Given the observed clustering of obesity, hypertension, inflammation, intermittent hypoxia, hyperglycemia, and insulin and leptin resistance, studies in humans in this area are extremely difficult and require innovative experimental approaches." (PMID 26781642, 2016). "In addition, bioactive molecules and hormones associated with obesity (such as leptin, angiotensinogen, aldosterone stimulating factor, dipeptidyl peptidase 4, and resistin) that could explain the metabolic effect of adipose tissue on glomerular hyperfiltration were not measured." (PMID 26495973, 2015). "Inversely, obesity-induced elevations in insulin and leptin are features of the metabolic syndrome and individually exert suppressive effects on steroidogenesis in the testes." (PMID 26366723, 2015). "Levels of adipokine, leptin, and adiponectin influence obesity and several signal transduction pathways involved in cell survival." (PMID 26779376, 2015). "These acquired methylation patterns were accompanied by a metabolic phenotype including obesity and increased leptin, insulin and glucose levels." (PMID 25954145, 2015). "The fcHFHS diet represents several features of the human obesity situation including increased fat mass, insulin resistance and peripheral leptin resistance compared to rats on the CHOW, fcHF, and fcHF diet." (PMID 26733840, 2015). "The aim of this study was to assess the regulation of serum irisin levels by nutritional status, leptin, and diet-induced obesity in rodents." (PMID 26568663, 2015). "Recently, there has been resurgence in glucagon research because of reports that the combination of glucagon and GLP-1 reduces obesity and restores leptin responsiveness in obese mice." (PMID 26909312, 2015). "Following studies have established the cardinal role of leptin in the pathogenesis of obesity (controlling body fat mass) and diabetes." (PMID 25704884, 2015). "By the same token, the minor variants -38g of rs200487063 and -30t of rs34104384 may cause a proportional increase in leptin production (by any tissues) and a proportional increase in the overall plasma leptin level, which is a known risk factor of hypertension as a complication of obesity." (PMID 26694100, 2015). "Elevated leptin levels coexist not only with obesity but also with diabetes and metabolic syndrome, the states that are connected with impaired immunity." (PMID 25306890, 2015). "In obesity, despite increased leptin levels, a dysregulation of energy balance is observed, suggesting that obese people are resistant to leptin." (PMID 26578976, 2015). "Ghrelin-circulating levels in obesity are low and are negatively correlated with body mass index (BMI), percent body fat, and leptin levels." (PMID 25960740, 2015). "Intrauterine growth restricted babies, piglets, and rodent pups have reduced leptin at birth and then propensity for obesity at adulthood; provision of leptin reverses this tendency." (PMID 25774292, 2015).
Obesity (continued). "Obesity-related changes include hypertrophy and hyperplasia of adipocytes leading to adipocytokine dysregulation manifested by high levels of leptin in obese state." (PMID 26036628, 2015). "Leptin amount is proportionally correlated with obesity, while adiponection amount is inversely related to obesity." (PMID 26694457, 2015). "Obesity is also related to insulin resistance through increased secretion of adipocytokines such as leptin and adiponectin." (PMID 26317422, 2015). "As the skyblue module, the steelblue module negatively correlated to obesity-related traits, especially BMI, adipocyte volume and leptin (r = -0.46, -0.48 and -0.51, respectively)." (PMID 25938420, 2015). "In this report we quantify the obesity phenotype and link this to altered leptin/neuropeptide signaling, and demonstrate abnormal microglia morphology in the IfitmDel animal." (PMID 25856311, 2015). "In women with uncomplicated abdominal obesity the leptin level was lower and the adiponectin level was higher than in women with complicated obesity." (PMID 26504811, 2015). "In vitro evidence has demonstrated that treatment of human umbilical vein endothelial cells with obesity-related levels of leptin (100 ng/mL) greatly increased expression of ET-1 compared to those levels encountered in normal weight humans (~10 ng/mL)." (PMID 26569331, 2015). "Recent lines of evidence support the role of elevated levels of leptin found in obesity in generating reactive oxygen and reactive nitrogen species and subsequent free radical formation." (PMID 25658689, 2015). "In overweight and obesity, leptin function is thought to be deregulated whereby individuals are desensitized to the hormone and as a result still experience a heightened desire to eat despite plentiful energy stores." (PMID 26593941, 2015). "Monogenic mutations such as those described for LEP, LEPR, POMC, and MC4R cause only a minority of obesity cases whereas in most individuals obesity is based on a polygenic predisposition amplified by an obesogenic Western lifestyle." (PMID 26470795, 2015). "Leptin and adiponectin are differentially expressed adipokines in obesity and cardiovascular diseases." (PMID 26064110, 2015). "Studies showed that physical activity can reduce the resting levels of these cytokines by reducing obesity, leptin and increasing the adiponectin and insulin sensitivity." (PMID 26687477, 2015). "Ob/ob mouse, db/db mouse, and fa/fa rat are monogenic models of obesity, which all target on leptin gene." (PMID 25954750, 2015). "After its discovery leptin became the great hope as an anti-obesity treatment because of its ability to reduce food intake and increase energy expenditure." (PMID 25871295, 2015). "The polymorphisms in leptin (LEP G-2548A) and leptin-receptor (LEPR Gln223Arg) seem to influence obesity and lipid metabolism among others." (PMID 26064921, 2015). "Studies have found that white adipose tissue becomes hypoxic as size and mass expand due to obesity, the level of leptin is thus directly related to body weight or fat." (PMID 25573199, 2015). "We chose leptin from among several factors in obesity to determine its role in glucose transport and expression of glucose transporters in lymphocytes." (PMID 25306890, 2015). "Further, adipocytes themselves secrete leptin and IL-6 after the macrophage infiltration and further increase the inflammatory response due in obesity." (PMID 26217222, 2015). "Monogenic obesity genes in the leptin-melanocortin pathway provide the link between adipose tissue and the hypothalamus, which are critical sites for balancing the energy need of the body." (PMID 26363598, 2015). "In vivo data from Hall and colleagues demonstrated that high-fat diet-induced obesity in male rats produced increases in circulating leptin by 3× along with hypertension, and this blood pressure response was significantly attenuated by an ETA antagonist." (PMID 26569331, 2015).
Obesity (continued). "There is a “complex interaction between obesity, insulin and leptin resistance, and the endocrine abnormalities in PCOS”." (PMID 26180527, 2015). "The homozygous condition of ob/ob is found also in humans and is characterized by very low leptin levels and severe obesity." (PMID 26347815, 2015). "In a previous study, we demonstrated that obesity improved survival due to increased leptin levels and improved cellular immunity." (PMID 25844479, 2015). "It has been consistently demonstrated that the obesity-related metabolic factor leptin is elevated in the circulation of pregnant women destined to develop PE." (PMID 26569331, 2015). "Diet-induced obesity also induces astrogliosis (along with activation of microglia), which prevents circulating metabolic feedback factors, such as leptin from accessing neurons." (PMID 26236282, 2015). "Adipokines such as adiponectin and leptin have been studied intensively for their relation to obesity, insulin resistance, and hyperglycemia and as potential proatherogenic mediators." (PMID 25915208, 2015). "Another relevant study displayed that fucoxanthin down-regulates stearoyl-coenzyme A desaturase-1 (SCD1), with subsequent improvement of insulin and leptin sensitivity, thus contributing to the prevention of obesity." (PMID 25871295, 2015). "Leptin is transported across the BBB by a saturable and unidirectional system, and impairment of leptin transport across the BBB has been reported in obesity, contributing to a leptin-resistant state." (PMID 25453257, 2015). "The role of the obesity cytokine leptin in breast cancer progression has raised interest in interfering with leptin's actions as a valuable therapeutic strategy." (PMID 25721149, 2015). "Decreased insulin resistance in leptin related obesity and fructose-induced metabolic syndrome was noted when lowering uric acid by uricosuric agents and xanthine oxidase inhibitors." (PMID 25629033, 2015). "Another study has shown that in a rat model of obesity, rapamycin was able to normalize elevated serum leptin by alleviating obesity and decreasing leptin synthesis in white adipose tissues." (PMID 25948792, 2015). "Leptin also has immune-modulatory effects and it has been suggested that this hormone links obesity with inflammation and hence with cardiovascular disease by such mechanisms." (PMID 25994184, 2015). "Unfortunately, obesity is always accompanied with increased leptin and decreased adiponectin in serum, negatively associated with desirable metabolic parameters." (PMID 26339623, 2015). "Multiple epidemiological, clinical and preclinical studies have shown the importance of adipocytokine leptin in mediating the molecular effects of obesity." (PMID 26036628, 2015). "Biomarkers of obesity (leptin, adiponectin), diabetes (glucose, insulin), inflammation (C-reactive protein, Interleukin-6, surface tumor necrosis factor receptor (sTNFR) I & II) and oxidative stress (F2-isoprostanes) were measured in stored blood samples." (PMID 26380096, 2015). "Further, pharmacological or genetic disruption of the NFκB pathways have been shown to restore leptin sensitivity and reduce adiposity in diet induced obesity." (PMID 25830092, 2015). "They believe that leptin resistance in obesity would prevent the high levels of leptin from inhibiting deposition of triglycerides in the heart." (PMID 26064110, 2015). "This hypothalamic leptin resistance has limited the usefulness of leptin as a treatment for obesity." (PMID 26381935, 2015). "A role for leptin in promoting pulmonary inflammation and bronchoconstriction has been demonstrated in murine models of obesity and asthma." (PMID 26770217, 2015). "Knocking out the leptin gene in mice manifested the role this hormone has in regulating appetite and, by extension, preventing obesity." (PMID 26635787, 2015). "Leptin, the adipose tissue cytokine, increases in obesity and promotes survival of cancer stem cells in vivo, consequently promoting breast cancer." (PMID 26107623, 2015).